TNF (tumor necrosis factor)
Diseases named in the same sentence as TNF in open-access papers (continued):
Sharing a sentence is not in itself a finding about the gene and the disease.
Obesity (continued). "To determine how obesity affects neuroinflammation in female mice, we examined the mRNA expression levels of proinflammatory cytokines (TNFα, IL1β, and IL6) and markers of microgliosis (Iba1) and astrogliosis (GFAP) in three distinct brain subregions (hypothalamus, hippocampus, and cerebral cortex)." (PMID 39230054, 2024). "In individuals with obesity, adipose cells release free fatty acids and cytokines, such as tumor necrosis factor-alpha, which inhibit phosphatidylinositide-3-kinase-dependent signal transduction pathways, resulting in decreased glucose absorption in the liver and skeletal muscles." (PMID 39441823, 2024). "First, obesity may lead to elevated levels of inflammatory cytokines such as tumor necrosis factor-α, interleukin-6, and C-reactive protein." (PMID 38577567, 2024). "Additionally, 49.7% of the cohort was affected by obesity, known to exacerbate inflammatory cytokine expression, as excess adipose tissue secretes elevated levels of pro-inflammatory adipokines like TNF-α and IL-6." (PMID 39408907, 2024). "Obesity has been shown to promote decreased adiponectin levels through an increase in the levels of inflammatory factors such as IL-6 and tumor necrosis factor-alpha (TNF-α) in adipocytes." (PMID 39456805, 2024). "Therefore, this study aimed to assess the safety of utilizing miR-130b-MVs for obesity treatment, revealing an upward trend in plasma levels of IL-6 and TNF-α after miR-130b-MV injection." (PMID 39591339, 2024). "Adipose tissue in obesity secretes proinflammatory cytokines like TNFα and IL-6." (PMID 39859981, 2024). "Considering the link between obesity and inflammation, we aimed to examine the early effects of bariatric surgery (laparoscopic sleeve gastrectomy) on inflammatory and anti-inflammatory cytokines (TNF-α, IL-6, IL-10)." (PMID 39180618, 2024). "Promoter methylation patterns are potential biomarkers that could be applied for managing obesity, and TNF-α gene expression in blood could be partly determined by dietary factors." (PMID 38542788, 2024). "Other proposed mechanisms suggest that empagliflozin enhanced fat utilization and browning, attenuated obesity-induced inflammation, and suppressed weight gain and insulin resistance by polarizing M2 macrophages and lowering plasma tumor necrosis factor-alpha (TNFα) levels in WAT and the liver." (PMID 39596449, 2024). "For example, obesity, inflammaging, cardiovascular disease, hypertension, and rheumatoid arthritis are characterized by elevated concentrations of circulating cytokines, such as IL-1b, IL-6, IL-8, IL-10, IL-13, TNF-α, and IFN-γ." (PMID 39408907, 2024). "Additionally, chronic treatment of obesity with leptin promotes preadipocyte differentiation and secretion of pro-inflammatory cytokine TNF-α." (PMID 39564133, 2024). "By increasing faecal butyric acid levels and hepatic SOD and GPx activity, with a decrease in lipid peroxidation and suppressed expression of TNFα, IL-6, iNOS, and NF-κB levels, purple maize anthocyanin efficiently demonstrated anti-obesity efficacy in C57BL/6 mice fed a high-fat diet." (PMID 39125340, 2024). "When evaluating plasma inflammatory parameters, it was observed that TNF-α was significantly higher in females and males from the obesity 1 and obesity 2 groups (obesity 1: 16.39 (1.17) pg/mL/p = 0.0003, and obesity 2: 16.33 (0.79) pg/mL/p = 0.0004) than control group 1." (PMID 39408365, 2024). "A genetic deficiency of IL-1 or TNF receptors was reported to suppress the development of insulin resistance in diet-induced obesity mouse models, and in healthy participants, intravenous infusion of TNF-α was reported to decrease whole-body glucose uptake in insulin clamp tests." (PMID 38347961, 2024).
Obesity (continued). "The third model selected in this study analyzed the progression of skin involvement in PsV by incorporating all available features, including several binary features newly created from multiclass features such as obesity, depression, hypertension, and TNF-α–targeting therapy (Multimedia Appendix 3)." (PMID 38738977, 2024). "Elevated levels of pro-inflammatory cytokines, such as TNF-α and IL-6, occur concomitantly with an increase in lipid content in white adipose tissue (WAT), contributing to the development of complications associated with obesity." (PMID 38542720, 2024). "The results indicated a significant increase in the expression of SPP1 and TNF-α due to obesity." (PMID 38956667, 2024). "It is known that obesity and insulin resistance are conditions where low-grade inflammation prevails, characterized by the secretion of pro-inflammatory cytokines (IL-1, IL-6, TNF-α)." (PMID 38474087, 2024). "In obesity and diabetes their mechanisms of action mostly rely on decreasing TNF-α and IL-6 levels." (PMID 38504163, 2024). "Adipose tissue in obesity secrets proinflammatory mediators such as TNF-α, IL-1β, and IL-6." (PMID 38317220, 2024). "In contrast to KLF15, furin, promotes obesity-induced inflammatory conditions by stimulating TNFα release from adipose tissue, modulating the activities of adipocytokines (including adipolin), thereby intensifying the vicious cycle caused by the inflammatory response and insulin resistance." (PMID 39308032, 2024). "In C57BL/6J (B6) obese mice induced by genetic obesity (db/db) and high-fat and high-sugar diet, nicotine inhibited the increase of F4/80 in obesity-induced inflammation and the levels of proinflammatory cytokines such as TNF-α, IL-6, IL-1β and iNOS in serum." (PMID 38681197, 2024). "Adipokines such as leptin and proinflammatory cytokines such as TNFα, IL-6 and IL-18 are involved in the pathogenesis of obesity-related insulin resistance in women with PCOS but seem also to be directly implicated in the pathogenesis of ovarian and adrenal dysfunction." (PMID 38540265, 2024). "Obesity in EMS is intricately linked to persistent inflammatory states, a connection underscored by our observation of reduced pro-inflammatory markers IL-1β and TNF-α alongside an elevation in the anti-inflammatory cytokine IL-10 within the serum." (PMID 38689728, 2024). "Moreover, obesity has been shown to impair the efficacy of psoriasis treatments, particularly fixed-dose biologics like TNF inhibitors, likely due to altered pharmacokinetics and increased systemic inflammation." (PMID 39769200, 2024). "However, few studies have examined the association between KITT(iv) and other parameters related to obesity and insulin resistance (such as visceral fat, adiponectin, and tumor necrosis factor [TNF]-α)." (PMID 38905235, 2024). "Therefore, it is important to discuss the influence that TNF-α has on adipocyte pathophysiology during the progression of obesity." (PMID 39275140, 2024). "We further analyzed the secretion patterns of 105 different cytokines and chemokines by THP-1 monocytes in response to 24 h incubation with OSAS and obesity related parameters hypoxia, tumor necrosis factor α (TNFα) and leptin using membrane based human cytokine arrays." (PMID 38172514, 2024). "Chronic hyperleptinemia due to obesity and elevated levels of inflammatory cytokines like interleukin-6 (IL-6) and tumor necrosis factor-alpha (TNF-α) are hypothesized to lower the CSD threshold, making the brain more susceptible to migraine triggers." (PMID 39456943, 2024). "Therefore, through fatty acid exposure, TNF-α stimuli, or macrophage co-culture, WAOs can be successfully applied to disease modeling and drug screening of obesity, T2DM, and NAFLD." (PMID 38505622, 2024). "Prior research has demonstrated that the degree of insulin resistance decreases with age, and TNF-α may be increased with obesity duration." (PMID 39456161, 2024).
Obesity (continued). "In addition, adipocytes of individuals with obesity secrete inflammatory cytokines, such as tumor necrosis factor α (TNFα) and interleukin-6 (IL-6), which induce an inflammatory state." (PMID 38327997, 2024). "Reports have shown a positive correlation between TNF-α and obesity and a negative correlation with weight loss, suggesting a link between TNF-α and adiposity." (PMID 39728103, 2024). "Obesity and overweightness are well-known proinflammatory metabolic disorders relating to high levels of inflammatory markers including interleukin (IL-)1β, IL-6, C-reactive protein, and tumor necrosis factor (TNF)α." (PMID 39337202, 2024). "Similarly, in pregnant mice with obesity, there are increased levels of inflammatory markers, including TNF-α, IL-6, interleukin-1β (IL-1β), nuclear factor kappa-light-chain-enhancer of activated B cells (NFκB) and interleukin-10 (IL-10) in the placenta." (PMID 38671859, 2024). "Obesity is accompanied by chronic inflammation characterized by elevated levels of pro-inflammatory cytokines such as tumor necrosis factor-alpha (TNF-α), C-reactive protein (CRP), and interleukins (IL-1, IL-6, and IL-18), with strong correlations between these inflammatory markers and body fat." (PMID 38794702, 2024). "The macrophages and adipocytes are the major TNFα and IL-6 sources in individuals with obesity." (PMID 38279016, 2024). "Additionally, adipose tissue dysfunction in obesity leads to the release of proinflammatory cytokines such as IL-6 and TNF-α that can directly interfere with insulin signaling within cells, further exacerbating insulin resistance (Fève and Bastard, 2009)." (PMID 39717478, 2024). "Specifically, TNF-alpha levels decreased in O-Rev females under an SD and in both sexes of this group under a WD, compared to the O-WD group, supporting the idea of a certain protection against diet-induced obesity." (PMID 39595945, 2024). "In this study, the characteristics of obesity-related inflammation in TNF-α-induced differentiated hMSCs were investigated to understand the mechanisms involved in probiotic LAB, WiKim39 and WiKim0124, and determine the contribution of metabolites to the obesity-related inflammatory response." (PMID 37940180, 2024). "Other factors inherent to the individual’s physiological condition may contribute to variations in cytokine levels, such as obesity, since adipose tissue induces the production of TNF-α." (PMID 39650644, 2024). "Additionally, in the state of obesity, adipose tissue releases various cytokines, such as tumor necrosis factor‐α (TNF‐α) and interleukin 6 (IL‐6), which play a role in chronic inflammation." (PMID 39606808, 2024). "TNF-α may affect glucose metabolism but aging and obesity prevent normal inhibition of TNF-α production, contributing to decreased insulin sensitivity in older men." (PMID 38794167, 2024). "Since obesity triggers a chronic low-grade inflammatory response, blood samples from all three dietary intervention groups were analyzed for inflammatory factors IL-6 and TNF-α." (PMID 37601677, 2023). "Histone acetylation was positively correlated with obesity indices, TNF-α, insulin, and HOMA-IR." (PMID 37862340, 2023). "Additionally, TNF-α levels were significantly elevated in the group with obesity compared to the normal group." (PMID 37862340, 2023). "Empagliflozin may attenuate obesity-induced inflammatory responses by limiting macrophage activity and lowering TNF-a expression, as was proposed by some investigators." (PMID 37566054, 2023). "Although the relationship between obesity and DM-2 remains unclear, tumor necrosis factor alpha (TNF-α) levels in adipocytes, and insulin and receptor dysfunction are thought to be some of the underlying mechanisms." (PMID 38813486, 2023).
Obesity (continued). "Obesity-related leptin resistance mechanisms and inflammatory factors (including tumor necrosis factor-α, interleukin-1β, and C-reactive protein) mediate inflammatory responses suppress hypothalamic-pituitary-gonadal axis function in obese men, leading to decreased body testosterone levels." (PMID 37361537, 2023). "This might suggest that TNF-α with hyperandrogenism may be one of the pathological mechanisms of PCOS with obesity." (PMID 37427330, 2023). "Finally, obesity-mediated adipocyte inflammation and necrosis results in a systemic meta-inflammation mediated by macrophages and cytokines such as TNFα and IL-8." (PMID 37396181, 2023). "In addition, FA treatment has been shown to reduce serum TNF-α levels in a mouse model of high-fat diet-induced obesity and serum IL-6 levels in formaldehyde-induced hepatotoxicity." (PMID 36836745, 2023). "In a previous study we reported that increased leptin level was related to obesity regardless of associated diabetes while elevated level of tumor necrosis factor-α was linked to obesity that is associated with diabetes." (PMID 36950695, 2023). "Since previous studies have documented that obesity reduces the response rate to anti-TNF-α agents in RA, the aim in this study was to determine whether BMI affects the response to rituximab in RA." (PMID 38813042, 2023). "Thus, incubation with margatoxin reduced TNFα and IL-6 secretion by adipose tissue in vitro and ShK-189 treatment reduced TNFα production in adipose tissue in mice fed with obesity-induced diet." (PMID 34623540, 2023). "Protective effects of the drugs may be through correlations between SIRT-1/adipokines/IGF-1 and PPARγ, improving the cross-talk between insulin resistance, obesity markers, liver dysfunction, and TNF-α." (PMID 36991247, 2023). "Prominent among the elevated obesity-associated circulating adipokines and cytokines are the C-reactive protein (CRP), Semaphorin-3C (Sema3C), Tumor Necrosis Factor-alpha (TNF alpha), Interleukin-6 (IL-6), Monocyte Chemoattractant Protein-1 (MCP1), and Interleukin-8 (IL-8)." (PMID 38068748, 2023). "Indeed, obesity promotes cancer through mechanisms involving ROS and is associated with the presence of adipokines, VEGF, TNFα and IL-6." (PMID 36670988, 2023). "A further study investigated the impact of TNF-α neutralization on IR via infusions with infliximab by performing a prospective, randomized double-blind placebo-controlled trial in healthy male patients suffering from obesity." (PMID 37239098, 2023). "TNF-α is well recognized for its role in obesity and its comorbidities." (PMID 37529617, 2023). "Second, visceral fat is also an active endocrine tissue, increased secretion of adipose-specific cytokines (e.g., leptin, IL-6, and TNF-α) in patients with obesity or abnormal adipose distribution also inhibits gonadotropin secretion, which in turn inhibits HPG axis." (PMID 38260153, 2023). "It is generally agreed that the activation and proliferation of NK cells in the VAT in the context of obesity also play important roles in IR and T2D through interaction with ATMs, triggering and amplifying the secretion of inflammatory cytokines, such as TNF-α and IL-6, by macrophages." (PMID 39872860, 2023). "Systemically, increased adipose tissue accumulation, as seen in obesity, can lead to increased production of interleukin 6 (IL-6), interleukin IL-1β (IL-1β) and tumor necrosis factor (TNF-α), pro-inflammatory cytokines able to disrupt the immune response at the maternal–fetal interface." (PMID 37111410, 2023). "In the presence of obesity, therefore, it seems that myocytes also release proinflammatory cytokines (myosins), such as IL-6 and TNFα, in a synergic effect of the activity of myocytes and adipocytes on metabolic dysregulation, aggravating insulin resistance and inflammation." (PMID 36626317, 2023). "Obesity and IR are connected to the pro-inflammatory cytokines TNF-α and IL-6." (PMID 36677054, 2023).
Obesity (continued). "Dysregulation of PVAT as a consequence of obesity leads to dysregulated production of adipokines and cytokines such as decreased hydrogen sulphide, NO, and adiponectin and increased leptin, IL-6, TNF-α, IL-12, hydrogen peroxide, and the renin–angiotensin–aldosterone system." (PMID 37372025, 2023). "The number of preadipocytes undergoing differentiation in the abdomen subcutaneous tissue is decreased due to elevated levels of mitogen-activated protein kinase kinase 4 (MAP4K4), which is engaged in the TNF-signaling pathway, leading to hypertrophic fat cells in conjunction with obesity." (PMID 37251328, 2023). "In this way, histone acetylation with respect to TNF and the resultant insulin resistance may encourage the emergence of the obesity phenotype." (PMID 37899888, 2023). "Furthermore, obesity during pregnancy is associated with increased levels of C-reactive protein (CRP), interleukin (IL)-6, tumor-necrosis factor-α (TNFα) and leptin." (PMID 37731394, 2023). "Reduced the levels of obesity-related TNF-α and IL-6, reduced fasting glucose and insulin levels." (PMID 36671814, 2023). "VL cases, as compared with MOD cases and controls, had higher prevalence of elevated serum hsCRP (>5 mg/L; 57%, 15%, and 22%, respectively; P = 0.004), detectable milk TNF-α (67%, 32%, and 33%, respectively; P = 0.04), and obesity (78%, 40%, and 22%, respectively; P = 0.003)." (PMID 36208911, 2023). "Additionally, TNF-α is involved in the development of various comorbidities, such as coronary atherosclerosis, obesity, ankylosing spondylitis, rheumatoid arthritis, inflammatory bowel disease, uveitis, and septic sweat gland." (PMID 36837593, 2023). "Interestingly, the inoculation of gut microbiome from children with obesity to mice resulted in the enrichment of colon and liver pro-inflammatory miRNAs, resulting in higher expression of pro-inflammatory markers such as TNFα and IL6." (PMID 37672200, 2023). "Salicylate treatment was able to overcome the inhibition of insulin signalling by TNF stimulation, implying that the IKKβ pathway may contribute to IR in Type 2 Diabetes and obesity by impinging on insulin signalling." (PMID 36175539, 2023). "In addition, IL-6, TNF-α, and CRP are repeatedly found to be elevated in a myriad of conditions linked to inflammation, such as obesity and smoking." (PMID 37213604, 2023). "In obesity, preadipocyte differentiation into mature adipocytes is promoted, as is the production of inflammatory cytokines (such as the Tumor necrosis factor alpha (TNF-α) and some interleukins such as IL-6, IL-1, and IL-18)." (PMID 37513229, 2023). "It is well known that obesity is characterized by the elevation of proinflammatory cytokines, including tumor necrosis factor-alpha (TNF-α), interleukin-6 (IL-6), and acute-phase proteins, such as C-reactive protein (CRP), leading to chronic subclinical inflammation." (PMID 37892400, 2023). "Moreover, it is worth noting that low-grade inflammation is a feature of both T2DM and obesity, and the expression of PTP1B was shown to be linked to that of pro-inflammatory cytokines such as tumor necrosis factor-α (TNF-α) and interleukins IL-1 and IL-6." (PMID 37298571, 2023). "Similarly, clinical studies show that NS has the potential to improve obesity by improving anthropometric parameters, restoring dyslipidaemia and reducing inflammatory markers TNF-a and SOD." (PMID 37765374, 2023). "A study conducted on diet-induced obese (DIO)-mice revealed that controlling obesity through exercise and diet control was found to be an effective means decrease the pulmonary TNF-α levels which result in decreased asthma severity in obesity-associated asthma." (PMID 37251328, 2023). "This review drew that probiotics might act as a role in regulating HDL-C, LDL-C, adiponectin, leptin and TNF-α in overweight or obesity children." (PMID 37542325, 2023).